FTO (FTO alpha-ketoglutarate dependent dioxygenase)
Diseases named in the same sentence as FTO in open-access papers (continued):
Sharing a sentence is not in itself a finding about the gene and the disease.
Obesity (continued). "Dysregulation of the FTO gene has been linked to various conditions, including obesity, T2D, and PCOS, through its direct effect on body weight and BMI, in addition to its impact on metabolic factors like IR, insulin sensitivity, serum glucose, and hyperandrogenemia." (PMID 40486662, 2025). "Thus, single nucleotide polymorphism (SNP) of FTO has been associated with an increased risk of obesity in genome-wide association studies (GWAS)." (PMID 40630163, 2025). "FTO gene polymorphism may be implicated in the etiopathogenesis of BC, both in FTO pre- and post-menopause women diagnosed with overweight/obesity." (PMID 40630163, 2025). "Notably, the rs9939609 polymorphism of the FTO (Fat Mass and Obesity Associated) gene has been linked to an increased risk of overweight and obesity in children and adolescents, with effects varying across populations." (PMID 40349719, 2025). "Genetic variants in the Fat mass and obesity associated (FTO) gene, encoding a m6A demethylase, have been consistently associated with body mass index (BMI) across multiple populations, suggesting a potential association between m6A and obesity." (PMID 41225618, 2025). "Second, this study was limited to only one SNP of the FTO gene, and other SNPs of obesity gene may have different associations with BC." (PMID 40630163, 2025). "The FTO gene, associated with obesity and metabolic syndrome, may also play an important role in the development of pre-eclampsia and its complications." (PMID 41234028, 2025). "The fat mass and obesity-associated (FTO) gene, implicated in energy expenditure and dietary preferences, may also influence the effectiveness of the LCKD." (PMID 40626223, 2025). "The FTO gene is known for its association with obesity and metabolic syndrome." (PMID 41234028, 2025). "Overall, this evidence supports the hypothesis that physical activity directly modulates molecular pathways altered by the FTO risk allele, thereby reducing obesity risk in genetically predisposed individuals." (PMID 41300761, 2025). "Growth and meat quality traits were evident through CAST (calpastatin, regulating muscle tenderness), FTO (fat mass and obesity‐associated gene, impacting fat deposition), GHR (growth hormone receptor) and MTOR (mechanistic target of rapamycin, controlling muscle protein synthesis)." (PMID 40859468, 2025). "The interacting FTO SNP (rs1421085) is noteworthy as it was one of the first polymorphisms to be linked to obesity: the fact that it interacts with the PGS for several obesity-related traits therefore suggests that its impact is partly mediated through polygenic background." (PMID 41332835, 2025). "For instance, the FTO gene is strongly associated with obesity risk." (PMID 41228239, 2025). "In 2017, a review on the fat mass and obesity-associated (FTO) genes and its related single nucleotide polymorphisms (SNPs) suggested that telomere attrition may be influenced by obesity-related inflammation, oxidative stress, and FTO-associated pathways." (PMID 40847086, 2025). "While this study supports a potential association between FTO rs9939609 polymorphism, obesity, and breast cancer (BC), the mechanistic pathways linking these variables remain speculative and require further validation in longitudinal or functional studies." (PMID 40630163, 2025). "Variants of the FTO gene have been associated with increased fat mass and obesity." (PMID 41303403, 2025). "This indicates that FTO polymorphisms related to obesity are likely via its demethylase activity." (PMID 41077815, 2025). "Some SNPs in the FTO gene were associated with the metabolic phenotype of obesity." (PMID 40662170, 2025). "Furthermore, a meta-analysis of multiple studies across various ethnic groups emphasizes that FTO’s role in breast cancer risk is often mediated by factors like obesity, estrogen receptor status, and metabolic health." (PMID 40630163, 2025).
Obesity (continued). "Understanding the role of obesity genetics, including FTO, will enable predictions of this association, which in turn may help identify the individuals at risk of obesity due to genetics." (PMID 39925495, 2025). "The findings imply that physical exercise might mitigate the elevated risk of Obesity caused by genetic vulnerability to FTO mutations." (PMID 41302083, 2025). "Specifically, we first report a flatter OGTT curve driven by the decreased 60’ min postload PG levels during OGTT in pregnancy in those mothers who carry fetuses with the FTO rs9939609/rs8050136 risk alleles that are major common genetic risk factors of obesity development later in life." (PMID 40877565, 2025). "Furthermore, regional autozygosity association analysis revealed an association between elevated ACR and a region in FTO, implicating its role in obesity, kidney disease, and cardiovascular conditions." (PMID 39994404, 2025). "The FTO rs9939609 variant is a major common genetic risk factor of adult obesity." (PMID 40877565, 2025). "Mechanistically, certain mutations in the FTO gene heighten obesity risk." (PMID 40040878, 2025). "FTO was the first gene that was associated with body mass index (BMI) and the risk of obesity." (PMID 39706986, 2024). "Indeed, the association of the FTO A-risk allele with the odds of obesity is attenuated by 27% in physically active adults." (PMID 39858551, 2024). "In the current study, we demonstrate that m6A modification is increased during ferroptotic cell death mediated by decreasing the expression of fat mass and obesity-associated protein (FTO), which down-regulates the expression of SLC7A11 and GPX4, thereby promoting ferroptosis in CRC." (PMID 38600610, 2024). "The analysis of the FTO gene in this study, reveals a clear gradient effect where the AA genotype is associated with the highest levels of obesity and emotional eating behaviors, whereas the TT genotype is linked to the leanest body compositions and the least severe emotional eating patterns." (PMID 39203789, 2024). "The A allele of the FTO gene may also be linked to obesity through a reduced capacity for fat oxidation during exercise, a topic that remains largely underexplored in the current literature." (PMID 39858551, 2024). "Interestingly, in our study, participants with the AA genotype of the FTO rs9939609 polymorphism exhibited several signs associated with obesity." (PMID 39858551, 2024). "FTO is an obesity‐related gene that is associated with metabolic disorders." (PMID 39092772, 2024). "FTO was first found to be associated with human obesity in 2007,62 and subsequently, its demethylation effect was discovered in 2011, which aroused great interest from researchers in the role of m6A in obesity." (PMID 38560499, 2024). "The occurrence of different polymorphic variants (SNPs) in the FTO gene may explain why unbalanced results in obesity have been obtained to date." (PMID 38892547, 2024). "FTO is a gene recently identified as being associated with obesity." (PMID 39660878, 2024). "Notably, GWAS have identified polymorphisms of the fat mass and obesity-associated (FTO) gene as the most prevalent risk alleles for obesity." (PMID 39876968, 2024). "Genomic studies have linked variations in the FTO gene to human obesity and metabolic disorders." (PMID 39494311, 2024). "The Fat Mass and Obesity-Associated (FTO) gene encodes a demethylase, which modulates RNA N6-methyladenosine (m6A) and plays a regulatory role in adipocyte differentiation and the pathogenesis of human obesity." (PMID 39336743, 2024). "Then, the FTO genes rs9939609 and rs17817449 were counted to explore whether polymorphisms were associated with overweight/obesity and metabolic parameters." (PMID 39483856, 2024).
Obesity (continued). "Another limitation is the existence of genetic variations in certain genes involved in lipoprotein metabolism that could be related to atherogenesis, such as the FTO gene, which is associated with obesity, insulin resistance, and BMI changes, respectively." (PMID 39683532, 2024). "Moreover, the genetic aspect of obesity, particularly the role of specific polymorphisms in genes like obesity-associated (FTO), leptin (LEP), leptin receptor (LEPR), and melanocortin 4 receptor (MC4R) genes, has been extensively studied." (PMID 38398881, 2024). "The study has limitations; the deviation from HWE in cases (but not in controls) may be due to the possible genetic association between FTO SNPs, obesity, and BC." (PMID 39040764, 2024). "In addition, obesity risk alleles at FTO rs1421085 significantly predicted more daily eating episodes (p = 0.001)." (PMID 38674326, 2024). "The FTO gene association with BMI and obesity risk was replicated in various studies." (PMID 39257882, 2024). "A genome-wide association study initially identified single nucleotide polymorphisms in the first and second introns of the FTO gene as being associated with increased BMI and a predisposition to obesity that persists from childhood into old age, thereby increasing the susceptibility to diabetes." (PMID 38706718, 2024). "Here, we report that ALKBH5 (AlkB Homolog 5) and FTO (FTO: Fat mass and obesity-associated protein), the two RNA demethylating enzymes, promote the translation of ATF4 mRNA in a transformed liver cell line (Hep3B) treated with the chemotherapeutic drug sorafenib." (PMID 39199320, 2024). "Another possible mechanism by which leptin could stimulate the hypertrophy program is through the activation of the fat mass and obesity-associated (FTO) gene, which has been shown to be closely related to obesity in experimental animals." (PMID 38256208, 2024). "However, the associations between obesity and the expression of the FTO gene in the kidney glomerulus, thyroid, and tibial artery are not well-established in the literature." (PMID 39711576, 2024). "Furthermore, mRNA levels of the N6-methyladenosine (m6A) demethylase, fat mass and obesity-associated protein (FTO), and the hydrolase matrix metalloproteinase-9 (MMP9), also increased in the mPFC." (PMID 38672038, 2024). "Regarding the effects of rs9939609 FTO polymorphism, the results showed that lifestyle factors including proper diet and physical activity may modify the influence of obesity risk alleles." (PMID 38556726, 2024). "The exact mechanism by which FTO variants increase the risk of obesity is still unclear." (PMID 38973101, 2024). "This balanced diet helps regulate energy intake, preventing rapid weight gain and reducing the risk of obesity, which may be influenced by the effects of the FTO gene." (PMID 39389470, 2024). "Similarly, for the allele A variant rs8050136 FTO gene, a high-carbohydrate diet will be associated with an increased risk of obesity." (PMID 39458556, 2024). "Various molecular studies on the correlation between obesity and tumorigenesis yield contradictory results as most of the single nucleotide polymorphisms lie in the intronic regions of the FTO gene and intron 1 and 2 show the strongest association with obesity." (PMID 39600630, 2024). "Moreover, there are other SNPs of FTO genes, such as rs9921255, rs9928094 and rs9930333, which showed a positive association with obesity and overweight." (PMID 38973101, 2024). "In addition to FTO, other obesity polymorphisms have been explored for their ability to regulate protein levels in individuals fed hypocaloric diets." (PMID 38281958, 2024). "It should also be noted that physical activity is a factor that may modulate the impact of FTO polymorphisms on obesity." (PMID 38892547, 2024).
Obesity (continued). "Following the recognition of the first m6A demethylase, namely fat and obesity-associated protein (FTO), mounting evidence has shown that polymorphism of the FTO gene leads to an increased occurrence of cardiovascular-related risk factors including obesity, diabetes, and inflammation." (PMID 39157458, 2024). "It is unclear whether DNA sequence variation in genes related to obesity, such as the FTO and MC4R genes, affects the outcome of weight loss intervention." (PMID 38674326, 2024). "It is possible that other SNPs within the FTO gene, such as rs1421085 and rs17817449, may also have influence as they have been associated with interindividual variations in obesity and appetite control." (PMID 39858551, 2024). "Previous studies reported that the A allele of FTO was associated with a higher risk of obesity in individuals who follow a poor diet (e.g., a high‐fat diet), while the effect of FTO risk alleles was attenuated in individuals who follow a healthy diet and regular physical activity." (PMID 38556726, 2024). "This suggests that the impact of FTO genetic polymorphisms on obesity susceptibility might be mitigated by socioeconomic variables." (PMID 39253342, 2024). "Moreover, quantitative‐real‐time polymerase chain reaction and western blot analysis were employed for detecting fat mass and obesity‐associated (FTO) and GPR177 levels, while m6A levels of GPR117 were analyzed via MeRIP." (PMID 39023405, 2024). "In addition, the expression of the fat mass and obesity-associated (FTO) gene has been found to affect hippocampal function and regulate BDNF processing, which helps to further explain the intricate relationship between RIF and BDNF." (PMID 38276070, 2024). "Early studies mainly explored obesity-causing genes from a single-gene perspective, and >20 causative genes have been confirmed to be highly associated with the development of obesity, including FTO, PPARG2, LEP, MC4R, and POMC." (PMID 39389470, 2024). "The FTO gene was identified as an important locus harboring common variants with an unequivocal impact on obesity predisposition and fat mass at the population level is being highly expressed in the hypothalamus, which controls food intake and energy expenditure." (PMID 39203789, 2024). "Furthermore, there are projects aim at assess the correlation between FTO polymorphisms and risk of developing diabetes in Mexican adolescents with overweight and obesity (NCT02886013), and features of metabolic syndrome in children with T1D (NCT01279161)." (PMID 38531882, 2024). "Further research into the molecular mechanisms and potential therapeutic targets related to FTO could open new avenues for the prevention and treatment of obesity and its associated metabolic disorders." (PMID 39744011, 2024). "Furthermore, this review has identified contradictory results regarding the association of well-established FTO gene variants with obesity risk among Malays, Chinese, and Indians." (PMID 39457458, 2024). "Our results showed that m6A levels were significantly increased in papillary thyroid cancer (PTC) and anaplastic thyroid cancer (ATC) samples, which may have been induced by the down-regulation of demethylase fat mass and obesity-associated gene (FTO)." (PMID 39379360, 2024). "However, it has been demonstrated that the association between FTO variation and obesity is sex-dependent." (PMID 39130748, 2024). "An Asian study reported the association of an obesity-related gene (FTO) with cataract." (PMID 38674349, 2024). "Research has demonstrated that an appropriate level of physical activity may overcome some of the adverse effects of the FTO rs9939609 variant on occurring obesity." (PMID 39858551, 2024). "Such as risk variants in FTO, a gene known to be involved in appetite control and eating behavior, is linked to a higher risk of obesity due to increased food intake and greater preference for foods with high energy and fat in children and adults but not in older adults [39, 40•]." (PMID 38806863, 2024).
Obesity (continued). "Therefore, identifying and comprehending the mechanisms underlying the connection between the FTO gene and obesity will aid in developing rational strategies for personalized management of obesity." (PMID 39253342, 2024). "Changes in the methylation pattern, together with a systemic inflammation, may affect genes such as the fat mass and obesity-associated gene (FTO) which are involved in the metabolic and inflammatory pathways." (PMID 39057082, 2024). "FTO gene was identified in association with obesity and body mass regulation." (PMID 39600630, 2024). "However, it has been shown that increased physical activity and a healthy diet can reduce the effect of FTO loci on obesity risk by 30–40%." (PMID 39458556, 2024). "However, the FTO gene was identified as a separate genetic risk factor for obesity for the first time in a genome-wide association study." (PMID 39758312, 2024). "Single-gene obesity studies have laid the foundation for childhood obesity research, and >100 loci have been confirmed to be highly associated with the development of obesity, including the FTO and PPARG2 genes." (PMID 39389470, 2024). "Park and Choi showed that FTO rs9939609 is associated with obesity risk in Korean women." (PMID 39040764, 2024). "Additionally, two FTO gene polymorphisms, rs9939609 and rs1558902, are explored as potential genetic links between psoriasis and obesity, although further research is needed to validate these associations." (PMID 38540130, 2024). "Variants in the obesity-associated gene FTO are suspected of being associated with obesity risk." (PMID 39458556, 2024). "However, according to a recent study in the Chinese population under the age of 18, FTO SNPs such as rs9939609, rs8050136, rs6499640 and rs1558902 have been found to be strongly linked to an increased risk of obesity." (PMID 38973101, 2024). "In our study, we aimed to explore whether two FTO gene polymorphisms, rs9939609 and rs1558902, could serve as potential genetic links between psoriasis and obesity." (PMID 38540130, 2024). "Different studies shown that FTO polymorphism have been related to obesity and overweight." (PMID 38973101, 2024). "Additionally, logistic regression analysis revealed that the FTO rs17817449 GT + TT, TT genotypes and TGs levels were independent risk factors for predicting overweight/obesity in DS children." (PMID 39706986, 2024). "Overexpression of FTO induced obesity in mice, associated with increased triglyceride deposition, whilst knockdown of FTO caused adipose tissue atrophy; furthermore, FTO overexpression promoted adipogenesis in preadipocytes, murine embryonic fibroblasts, and porcine intramuscular preadipocytes." (PMID 37375547, 2023). "Additionally, the investigation of the potential pleiotropic effects of BMI-associated single-nucleotide polymorphisms showed comparable results with the isolated effect of the FTO gene variant, which emphasizes its important role in obesity." (PMID 36980866, 2023). "FTO has a strong association with obesity in humans; FTO was first identified to be an obesity sensitivity gene according to a genome-wide association study in 2007 and FTO was shown to be highly expressed in the abdominal and subcutaneous adipose tissues of obese individuals." (PMID 37375547, 2023). "While variations in the first intron of the fat mass and obesity-associated gene (FTO, rs9939609 T/A variant) have long been identified as a major contributor to polygenic obesity, the mechanisms underlying weight gain in risk allele carriers still remain elusive." (PMID 37223038, 2023). "Research looking for early predictors of effective weight loss could help patients with the high-risk genotypes of the fat mass and obesity-associated (FTO) gene who have difficulty with effective weight loss achieve better treatment results." (PMID 37626800, 2023). "FTO is an obesity-susceptible gene identified through genome-wide association studies." (PMID 36352530, 2023).